MYC (MYC proto-oncogene, bHLH transcription factor)
Diseases named in the same sentence as MYC in open-access papers (continued):
Sharing a sentence is not in itself a finding about the gene and the disease.
diffuse large B-cell lymphoma (continued). "In situ and ex vivo analysis featured such tumours as activated type of diffuse large B cell lymphoma (ABC-DLBCL), expressing BCL2 and c-MYC, but not BCL6, with activated STAT3 signaling." (PMID 36503430, 2022). "ATRi (AZD6738) and WEE1i (AZD1775) display differential activity in a subpopulation of non-germinal-center-B cell (non-GCB) diffuse large B-cell lymphoma (DLBCL) cell lines characterized by high MYC oncogene expression and cyclin-dependent kinase inhibitor 2A/B (CDNK2A/B) deletion." (PMID 33167404, 2020). "Quantitative multiplexed microscopy reveals that a subpopulation of cells that coexpress MYC and BCL2 without BCL6 govern clinical outcomes in diffuse large B-cell lymphoma, underscoring the importance of analyzing protein coexpression patterns at single-cell resolution." (PMID 37071673, 2023). "As an example, patients with diffuse large B-cell lymphoma (DLBCL) who harbor a translocation at the c-MYC locus have less favorable rates of response to therapy and disease free survival compared to patients without the mutation, owing to the oncogenic effects of c-MYC." (PMID 29765528, 2018). "Intriguingly, within diffuse large B-cell lymphoma (DLBCL), MNDA expression is more prevalent in the non-germinal center B-cell (non-GCB) subtype and the BCL2/MYC double-expression group, displaying a correlation with CD5 expression—a finding that merits further exploration." (PMID 40386782, 2025).
liver cancer (265 papers, 2004 to 2026). An epithelial or non-epithelial malignant neoplasm that arises from the liver. "Liver cancer is a leading cause of cancer-related death due to the shortage of effective therapies, and MYC overexpression defines an aggressive and difficult-to-treat subset of patients." (PMID 41849351, 2026). "Focusing on the expression of STAT1, notably, the inhibition of MYC in liver cancer is linked to elevated STAT1 expression, which upregulates PD-L1 and contributes to immune escape by tumor cells." (PMID 40909948, 2025). "Upregulated pathways were associated with MYC targets, cellcycle, liver cancer, dividing cells, methylation, SOX4 targets, IL6deprivation, senescence and tumor microenvironment." (PMID 40821580, 2025). "To test this, we induced liver cancer by transfecting Sleeping Beauty constructs encoding for the oncogenes c-MYC and AKT (constitutive active by myristoylation and tagged with HA) into normal hepatocytes." (PMID 39195268, 2024). "Gains of chromosome 8q22-24 region, encoding c-MYC are amongst the earliest genomic events associated with liver cancer development." (PMID 35008356, 2021). "The entire process illustrates the impairment in cell growth and death caused by the synergistic effect of HBx and c-MYC that trigger the development of liver cancer after a prolonged period of latency." (PMID 28422055, 2017). "In fact, hypomethylation of the c-MYC gene has been linked with liver cancer development, indicating that the state of DNA methylation can be used as a diagnostic tool for chronic liver damage." (PMID 28422055, 2017). "In conclusion, we present an oncogenic role of FAM83H in liver cancer, which is closely associated with the oncogene MYC." (PMID 28607447, 2017). "Contrary to what we expected, MYC activation was only associated with increased apoptosis in the hepatocytes of liver cancers." (PMID 15455033, 2004). "Therefore, the changes in the expression levels of ESR1 and FOBS genes in liver cancer inhibited HALLMARK MYC TARGETS V2 pathway, while HALLMARK HEME METABOLISM, HALLMARK COAGULATION and HALLMARK UV RESPONSE_DN pathways were activated." (PMID 34238253, 2021). "Moreover, it has been demonstrated that MYC activation is a major genetic event towards liver cancer development, a recent study linked liver cancer formation with amino acid transporters regulated by MYC and the activation of the mTORC1 signaling pathway." (PMID 32934298, 2020). "To further investigate the in vivo function of NLRP5, we acquired mice with spontaneous liver cancer expressing Alb-Cre+/MYC+, as detailed in the Methods section." (PMID 41050084, 2025). "Here, we dissect the distinct cell fitness in 2D (normoxia vs. chronic hypoxia) vs 3D (normoxia) culture conditions for an MYC-driven murine liver cancer model." (PMID 40326560, 2025).
liver cancer (continued). "The finding that liver cancers can be initiated by over-expressing MYC alone suggests that its cryptic oncogenic tendencies emerge only when it is aberrantly over-expressed and engages low-affinity target genes that are normally not subject to its control." (PMID 41440033, 2025). "Here we dissect the distinct cell fitness in 2D (normoxia vs. chronic hypoxia) vs 3D (normoxia) culture conditions for a MYC-driven murine liver cancer model." (PMID 38853928, 2025). "In order to investigate if the anti-tumoral effect of panobinostat is selective on MYC overexpressing hepatoblastoma or liver cancer in general, we phenocopied both scenarios in respective liver cancer mouse models." (PMID 39529166, 2024). "The study also highlighted that high extracellular copper concentrations promoted cell growth, migration, and invasion of liver cancer cells by upregulating MYC oncogene and modulating MYC/CTR1 axis." (PMID 38970072, 2024). "In line with the elevated expression of SLC1A5 and SLC7A5 in liver cancer, Trp levels were elevated in livers of mice upon MYC upregulation, as measured by tandem mass spectrometry (LC-MS/MS)." (PMID 38769298, 2024). "We noted that BETi decreased MYC levels in liver cancer cells, and MYC targets were identified as the top-ranked gene sets with altered expression by BETi." (PMID 39872506, 2024). "On the other hand, studies have indicated that SRC-2 can coactivate anti-tumor target genes, thereby inhibiting MYC-induced liver cancer progression." (PMID 39634176, 2024). "It is reported that c‐MYC is one of the downstream molecules activated by YAP to promote cell proliferation in liver cancer." (PMID 38292328, 2024). "Then the inactivation of MYC can lead to differentiation and dormancy of liver cancer cells, thus inducing sustained regression of liver cancer." (PMID 37393552, 2024). "To test the importance of Trp for the initiation of MYC-driven liver cancer, we compared mice overexpressing MYC in the liver that were fed with control, Low-Trp, or No-Trp diets for 21 days." (PMID 38769298, 2024). "As an oncogene, MYC is frequently deregulated across various cancer types, including breast cancer, liver cancer, colorectal carcinoma, multiple myeloma, and lymphomas, frequently inducing a dependency on the oncogene for disease progression." (PMID 36684069, 2023). "Our previous research has shown that a mouse liver tumor model of another form of liver cancer, hepatoblastoma (HB), required c-MYC for HBs to achieve maximal tumor growth." (PMID 37628798, 2023). "A high concentration of copper element can stimulate the proliferation, migration, and invasion of liver cancer cells by modulating the v-myc avian myelocytomatosis viral oncogene homolog (MYC)/CTR1 axis." (PMID 37427098, 2023). "With treatment of the Arf1 inhibitors, we observed increased CCL5 levels in the serum of mice bearing CT26 tumor and upregulated mRNA level of CCL5 in MYC-ON mouse liver cancer." (PMID 39872623, 2023). "First, using breast, lung and liver cancer samples collected from 30 patients at a hospital, we examined the difference in relative mRNA expression of MYC and TAF10 between adjacent non‐tumour tissues and cancer tissues." (PMID 36639831, 2023). "Concurrent inhibition of both targets via SSO therapeutic or pharmacological agents offers a novel and effective therapeutic strategy against MYC‐driven cancer, particularly MYC‐driven liver cancer." (PMID 36684069, 2023). "Nonetheless, opposite results from a recent study were showing a role for c-MYC in lineage commitment in K-Ras-driven primary liver cancer development." (PMID 37627221, 2023).
liver cancer (continued). "We fully expect this study will facilitate the future development of new treatment strategies targeted towards MYC+ TICs that arise in chemoresistant liver cancer patients." (PMID 37117191, 2023). "The in vitro and in vivo models utilized MYC to induce liver progenitor cells and produce liver cancer stem cells." (PMID 37993901, 2023). "We also observed enhanced mRNA levels of these downstream target genes of the PPARγ signaling in the MYC-ON mouse liver cancer treated with Arf1 inhibitors." (PMID 39872623, 2023). "We established a MYC-related ceRNA triple network in colon adenocarcinoma from the experience of our previous ceRNA network construction for liver cancer." (PMID 35847359, 2022). "Phb1 has also been shown to negatively regulate human and mouse liver cancer tumorigenesis through the downregulation of key oncogenes such as c-MYC." (PMID 35668443, 2022). "The activation of MYC is very important in the tumorigenesis of liver cancer, and its inactivation can lead to the continuous regression of HCC." (PMID 35356132, 2022). "Similar results have previously been observed in fibrosarcoma and liver cancer cells where menin was characterized as a critical cofactor for MYC-mediated transcription, that promotes growth of tumours with deregulated MYC expression." (PMID 36333801, 2022). "For miRNAs miR-17-5p, miR-9, and miR-185-5p, positive feedback was shown with MYC gene expression; transcription factor c-Myc stimulates transcription of these miRNAs in liver cancer cells." (PMID 34440124, 2021). "Regulation of MYC gene expression by miRNAs of the miR-320 family has been shown for liver cancer cells." (PMID 34440124, 2021). "MiRNA let-7, miR-148a-5p, miR-363-3p, miR-744-5p, miR-599, miR-9, miR-185-5p, miR-526b, miR-17-5p, and miR-122-5 are also involved in regulating the expression of the MYC proto-oncogene in liver cancer cells." (PMID 34440124, 2021). "MYC increases catabolism of glucose and glutamine in liver cancer, while MYC-driven lung tumors show increased expression of glutamine synthetase and glutaminase." (PMID 33652667, 2021). "Both MYC and MYC/Twist1 mice were observed to develop multifocal liver cancer, while only MYC/Twist1 mice developed lung metastases." (PMID 31933479, 2020). "This justifies further exploration of the interplay between m1A and the MYC pathway in the progression of liver cancer." (PMID 32934298, 2020). "Using mouse models of liver cancer induced by tissue-specific overexpression of MYC and MET, the effect of these two oncogenes on metabolic alterations in developed HCC were investigated by Yuneva and collaborators." (PMID 33182674, 2020). "Comparison of relative percentage of M2 macrophage subpopulation, derived using CIBERSORT analysis of Liver cancer TCGA cohort of 373 patients with tumors stratified as MYC/TWIST1High or MYC/TWIST1low (*p<0.05)." (PMID 31933479, 2020). "These bioinformatics analyses provide unbiased support of the activation of BRG1 in c-MYC induced liver cancer development." (PMID 32019910, 2020). "In our previous study, we demonstrated that FAM83H was an intermediate of the oncogene MYC on the MYC-mediated proliferation and invasiveness of liver cancer cells." (PMID 32564009, 2020). "Our analysis revealed HCSC important hubs as candidate regulators for targeting hepatic cancer stemness such as, miR-148a, miR-214, E2F family, MYC and SLC7A5." (PMID 30944375, 2019). "Obtained results disclosed that Lanatoside C inhibits Wnt/β-catenin signaling, along with Cyclin D1 and c-MYC expression in breast, lung, and liver cancers." (PMID 31783627, 2019).
liver cancer (continued). "It has been proved that miR‐198 has the capacity to suppress liver cancer, and we decided to investigate the connection between miR‐198 with proto‐oncogene MYC to see if there is another mechanism behind the suppression caused by miR‐198." (PMID 30378283, 2018). "In this study, we would like to figure out the relationship and the mechanism of FOXP3, miR‐198, and MYC in liver cancer." (PMID 30378283, 2018). "Based on this rationale, we investigated the oncogenic role of FAM83H in HCC in conjunction with the oncogene MYC in liver cancer cells and human HCC tissue samples." (PMID 28607447, 2017). "This led to the identification of Steroid Receptor Coactivator 2 (SRC-2, also known as NCOA2, TIF2, GRIP1) as a novel gene that functions to restrain MYC-induced liver cancer." (PMID 28273073, 2017). "For example, copy number gains of SRC-2 are frequent in liver cancer, although this is likely due to the proximity of this gene to the MYC gene on chromosome 8q." (PMID 28273073, 2017). "This work provides important new insights into the mechanism of tumor suppression by SRC-2 in MYC-induced liver cancer." (PMID 28273073, 2017). "Thorgeirsson and colleagues also showed that activation of c-MYC is required to reprogram adult hepatocytes into hepatic cancer stem cells (CSCs), which promotes malignant progression." (PMID 28422055, 2017). "In contrast, invasive liver cancers regressed after MYC inactivation, but residual tumor cells remained dormant and immediately restored their neoplastic features upon MYC reactivation." (PMID 28028012, 2017). "An unbiased forward genetic screen previously revealed a tumor suppressor role for the Steroid Receptor Coactivator 2 (Src-2) in liver cancer driven by the MYC oncogene." (PMID 28273073, 2017). "The pre-clinical findings showing significant improvement in the survival of the MYC induced liver cancer mice indicates the therapeutic potential of AXT050 on the subset of MYC amplified HCC patients." (PMID 29254183, 2017). "MYC is amplified in 40–60% of human HCCs and a number of studies have previously documented 8q gains in a significant fraction of liver cancers." (PMID 28273073, 2017). "It has been shown that glutamine metabolism switches from GLS2 to GLS1 in MYC-induced mouse liver cancer." (PMID 25844758, 2015). "Modest let-7 overexpression abrogated MYC-driven liver cancer by antagonizing multiple let-7 sensitive oncogenes." (PMID 26445246, 2015). "MYC liver cancers show a dramatic suppression of let-7, rendering it especially sensitive to let-7 replacement." (PMID 26445246, 2015). "We conclude that MYC overexpression in adult hepatocytes results in the formation of highly malignant liver cancers with features consistent with human HCC." (PMID 15455033, 2004). "We discovered that MYC-driven liver cancers catabolize alanine in a GPT2-dependent manner." (PMID 41849351, 2026). "In this study, we used an MYC-driven murine liver cancer model, and successfully identified context-specific fitness genes and pathways, as well as commonly shared fitness genes, in monolayer culture under 21% and 1% oxygen tensions and 3D spheroid culture under 21% oxygen tension." (PMID 40326560, 2025). "This dynamic suggests that concurrent targeting of MYC and PD-L1 could provide a synergistic approach to liver cancer therapy." (PMID 40909948, 2025). "The liver cancers that develop in response to MYC over-expression appear quite rapidly." (PMID 41440033, 2025). "MYC oncogene overexpression promotes tumorigenesis in various tumors, including liver cancer." (PMID 38343446, 2023). "However, SLC38A4 has been reported to function as a tumor suppressor in liver cancer through its modulation of Wnt/β-catenin/MYC/HMGCS2 axis acativation." (PMID 36599932, 2023).